CYP2B6 (cytochrome P450 family 2 subfamily B member 6)
Diseases named in the same sentence as CYP2B6 in open-access papers (continued):
Sharing a sentence is not in itself a finding about the gene and the disease.
toxicity (1 paper, 2013). The degree to which an agent can damage an organism. "While this study demonstrates influence of CYP2B6 genotype on efavirenz plasma concentrations which predicted neuropsychiatric toxicity, we did not observe a direct significant relationship between genotypes and neuropsychiatric toxicity but rather a tendency." (PMID 23734829, 2013).
cancer (50 papers, 1998 to 2025). A tumor composed of atypical neoplastic, often pleomorphic cells that invade other tissues. "Variability in CYP2B6 polymorphisms between populations indicates that cancer patients in various ethnicities will respond variably to CP therapy." (PMID 34322158, 2021). "Genetic variation in CYP3A4 and CYP2B6 have previously been associated with gonadotoxicity after cancer treatment." (PMID 34572825, 2021). "The pathway is a known mediator of fibrosis and suppressor of vascular invasion via cancer-associated fibroblasts (CAFs), potentially providing this subgroup with a more immunoprotected microenvironment.CYP2B6, CYP1A2, and CYP3A4 were associated with the “Chemical carcinogenesis” pathway." (PMID 40349011, 2025). "Furthermore, to fully comprehend the potential of the CYP2B6 candidate gene for cancer susceptibility, additional research, including large sample sizes, gene-gene, and gene-environment interactions, is needed." (PMID 38560574, 2024). "CYP2B6*9 was previously reported to be associated with cancer risk." (PMID 38560574, 2024). "To elucidate the contribution of CYP3A4 and CYP2B6 to DOX resistance in the three cancer spheroid models, we examined the effects of their siRNA-mediated inhibition on DOX resistance." (PMID 37958656, 2023). "In addition, CYP2D6, CYP3A4, CYP2B6, and CYP2C19 are implicated in anti-cancer metabolism, influencing their efficacy." (PMID 39062040, 2024). "The present study further develops this strategy with the introduction of a replication-defective adenovirus that co-expresses the prodrug-activating P450 enzyme CYP2B6 and the pan-caspase inhibitor p35, and is shown to augment bystander killing and the overall anti-cancer response." (PMID 20836875, 2010). "The present approach, involving the expression of CYP2B6, its redox partner P450 reductase, and p35 from a single replication-defective viral vector, may also be extended to cancer cell-replicating viral vectors." (PMID 20836875, 2010). "Moreover, since chemo-resistance due to changes in the expression and activity of CYP450 enzymes has been widely documented in several cancer types, CYP2B6 tumor expression could be related to tumor therapy response." (PMID 29914177, 2018). "Cyclophosphamide (CPA), a prodrug used in cancer therapy, is activated by CYP2C19, CYP2C9, CYP3A4, and CYP2B6 to treat some autoimmune disorders." (PMID 31998435, 2020). "These qPCR results confirmed a similar distribution of gene expression; overexpression of CYP1B1, CYP7A1, CYP17A1, and CYP19A1, and repression of CYP1A2, CYP2B6, CYP2C19, and CYP26A1 was observed in cancer tissues." (PMID 31258835, 2019). "This analysis showed that each of these cancer types has a distinct pattern of expression for CYP1A2, CYP2B6, and CYP2C19." (PMID 31258835, 2019). "Cyclophosphamide, a nitrogen mustard alkylating prodrug, requires metabolic activation and undergoes CYP2B6/CYP2C9 mediated oxidation to induce DNA damage and cell death in target cancer cells." (PMID 25669983, 2015). "GREAT also reported that HepG2-enriched windows were close to many cancer genes HPX, HPN, LCAT, TST, GSTM1, CEPBA, CYP2B6." (PMID 25522020, 2014). "In this work we demonstrated that a biosensor based on cytochrome P450 (CYP1A2, CYP2B6 and CYP3A4) and carbon-nanotubes enable the identification of different anti-cancer drugs, thus providing an innovative solution for point-of-care drug monitoring." (PMID 22778656, 2012). "Moreover, other studies have shown that the genotype of CYP2B6, or other CYPs involved in Cy metabolism, do not affect Cy kinetics and suggest that clinical factors such as patient age and cancer grade may be more significant." (PMID 26544874, 2015).
tumor (49 papers, 1993 to 2026). "Regarding tumor occurrence, our results indicate that the GT variant in CYP2B6 rs3745274 in recipients was statistically associated with an increased risk of tumor incidence during follow-up (p-value: 0.048)." (PMID 40761554, 2025). "Notable associations include survival related to ABCB1 and ABCC2 variants, tumor occurrence linked to CYP2B6 rs3745274, and renal function affected by multiple pharmacogenes." (PMID 40761554, 2025). "•CYP2B6 rs3745274 GT variant in recipients was associated to lower tumor and DM occurrence risk." (PMID 40761554, 2025). "Increased tumor risk correlated with ABCC2 variants in donors and decreased risk with CYP2B6 rs3745274 in recipients." (PMID 40761554, 2025). "According to the model with CYP2B6 SNVs or haplotypes, the primary tumour response was better in patients under 1.5 years than in older children, and girls were found to expect more favourable therapeutic outcomes than boys in both models (P = 0.03)." (PMID 37479763, 2023). "No protein of the anticipated size corresponding to CYP2B6 or CYP2S1 was detected in the tumor tissues by the commercially available (CYP2B6) or homemade (CYP2S1) antibodies." (PMID 25526449, 2014). "Presently, we investigate ways to increase the bystander cytotoxicity of cytochrome P450-based GDEPT by inhibiting the caspase 9-dependent apoptotic death that occurs in tumor cells infected with adenovirus expressing the CPA-activating P450 enzyme CYP2B6." (PMID 20836875, 2010). "The expression of p35 in Adeno-2B6/p35-infected tumor cells inhibited caspase activation, delaying the death of the CYP2B6 "factory" cells that produce active CPA metabolites, and increased bystander tumor cell killing compared to that achieved in the absence of p35." (PMID 20836875, 2010). "p35 gene delivery is shown to inhibit CPA-induced apoptosis of the CYP2B6-transduced tumor cells, which in turn leads to increased killing of bystander tumor cells, as verified by the decrease in bystander cell colony survival seen with two different CPA treatment schedules." (PMID 20836875, 2010). "Since CYP2B6 has high hydroxylase activity for CPA, it has been proposed to sensitize tumor cells to the action of this drug by in situ expression of this enzyme with gene therapy." (PMID 29914177, 2018). "Purified protein standards (CYP2B6, CYP2S1, and CYP3A4), MT-3 cells lysate (AKR1C2), human liver lysate (AKR1C1 and CBR1), and a pool of tumor samples (AKR7A3) were used as a calibrator for comparison of variability among membranes." (PMID 25526449, 2014). "Conversely, hepatic periportal markers (e.g., ALDOB, HAL, ASS1) and a subset of CYP-related proteins (e.g., CYP2A6, CYP2A7, CYP2B6) were either absent or downregulated in the tumor region." (PMID 39567475, 2024). "CYP2B6 also plays major role in activating CPA in the liver by oxidising the prodrug to a 4-hydroxycyclophosphamide (4-OH-CPA) which subsequently produces a cytotoxic alkylating agent that damages DNA and eradicates tumour cells." (PMID 33809117, 2021). "On a genetic level, a comparable study in a set of 20 paired samples of tumour and adjacent normal breast tissues from patients with infiltrating ductal carcinoma identified the expression of CYP1B1, CYP2B6, CYP2C, CYP2D6, CYP2E1, CYP4B1 and CYP11A1 in both tumour and control tissues." (PMID 33809117, 2021). "No data exist about the expression of the CYP2B6 protein in this tumour." (PMID 14970873, 2004). "Concentrations of Gamitrinib that trigger tumor cell killing (IC50 ~1-4 μM) do not affect cytochrome P450 isoforms CYP1A2, CYP2A6, CYP2B6, CYP2C8 or ion channel conductance (Nav1.5, Kv4.3/KChIP2, Cav1.2, Kv1.5, KCNQ1/mink, HCN4, Kir2)." (PMID 35129069, 2022).
infection (36 papers, 2009 to 2025). The state of being infected such as from the introduction of a foreign agent such as serum, vaccine, antigenic substance or organism. "Regarding CYP2B6, a higher risk of infection was observed in patients with a CYP2B6 metabolizer gene variant (rs2279343 GA)." (PMID 35214086, 2022). "On the other hand, the GA genotype in rs2279343 of CYP2B6 gene in the recipient was selected as a predictive variable by elastic net and associated with a higher risk of infection (OR: 1.116; p-value = 0.086)." (PMID 35214086, 2022). "Genetic variants in CYP2B6 metabolizer gene rs2279343 demonstrated an association with a risk of infection." (PMID 35214086, 2022). "Only the GA variant in rs2279343 of recipient CYP2B6 gene demonstrated an association with higher risk of infections, as observed in the whole panel study, though the OR was 1.240." (PMID 35214086, 2022). "Reduced activity of CYP2B6 enzyme due to gene polymorphism is associated with increased response to drug sensitivity and infection." (PMID 34752660, 2021). "In addition, genetic variants in CYP2B6 metabolizer gene proved association with higher risk of infections." (PMID 35214086, 2022). "Lysates of 293 cells infected with Adeno-2B6 or Adeno-2B6/p35 contained similar levels of CYP2B6 protein 48 and 72 hr post infection (top)." (PMID 20836875, 2010).
hematological malignancies (2 papers, 2020 to 2024). "Several studies provide evidence for the pathogenic role of the CYP2B6 (G516T) polymorphism in the susceptibility to hematological malignancies." (PMID 38560574, 2024).
infectious disease (2 papers, 2022 to 2025). A disorder directly resulting from the presence and activity of a microbial, viral, or parasitic agent in humans. "For example, for a representative group of patients with infectious diseases, up to €8182 were saved for each patient with CMV treated with interferon, or €43,549/year for HIV patients treated with efavirenz by genotyping IL28 or CYP2B6, respectively." (PMID 35057056, 2022).
psychiatric disease (1 paper, 2013). "Adjusted analyses showed that significant correlates for nonresponders were HCV coinfection (adjusted odds ratio, AOR = 6.42, P = 0.03), psychiatric diseases (AOR = 2.71, P = 0.02), alcohol problems (AOR = 2.25, P = 0.02), and CYP2B6 A785G (AOR = 1.74, P = 0.10)." (PMID 24455721, 2013).
CYP2B6 also shares sentences with these, for which no sentence is quoted: congenital adrenal hyperplasia (6 papers); Hypertension (6); cardiovascular diseases (5); diabetes (5); endometriosis (5); Hepatic steatosis (5); prostate carcinoma (5); allergies (4); COVID-19 (4); metabolic disease (4); non-alcoholic fatty liver disease (4); Parkinson disease (4); Sepsis (4); Hepatitis (3); melanoma (3); neutropenia (3); pancreatic cancer (3); vitamin D deficiency (3); 21-hydroxylase deficiency (2); 3-β -hydroxysteroid dehydrogenase deficiency (2); acute myeloid leukemia (2); acute renal failure (2); Adrenocortical Carcinoma (2); Alzheimer disease (2); anemia (2); autoimmune hepatitis (2); chronic kidney disease (2); dengue (2); heart failure (2); Hypocalcemia (2).
A further 87 diseases each share a sentence with CYP2B6 in 2 papers or fewer.